SLC27A6 (solute carrier family 27 member 6)
Description:
Mediates the import of long-chain fatty acids (LCFA) into the cell by facilitating their transport at the plasma membrane. Also functions as an acyl-CoA ligase catalyzing the ATP-dependent formation of fatty acyl-CoA using LCFA and very-long-chain fatty acids (VLCFA) as substrates (By similarity). Plays a pivotal role in regulating available LCFA substrates from exogenous sources in tissues undergoing high levels of beta-oxidation such as the heart.
Synonyms: ACSVL2; FACVL2; FATP6; VLCS-H1
Tractability: Antibody: UniProt places it where antibodies can reach, with high confidence; its Gene Ontology location is reachable by antibodies, with high confidence; UniProt predicts a signal peptide or a membrane-spanning region. PROTAC: ubiquitination databases record sites on it.
Gene: Protein-coding gene on chromosome 5 (128,538,013 to 129,036,767, forward strand). Ensembl gene ENSG00000113396.
Subcellular location: Cell membrane, sarcolemma; Cell membrane
Subcellular location (Human Protein Atlas): Nuclear bodies
Pathways (Reactome):
Transport of small molecules: Transport of fatty acids
Gene Ontology:
Molecular function: fatty acid transmembrane transporter activity; long-chain fatty acid transmembrane transporter activity; long-chain fatty acid-CoA ligase activity; arachidonate-CoA ligase activity; very long-chain fatty acid-CoA ligase activity
Biological process: long-chain fatty acid import into cell; long-chain fatty acid metabolic process; long-chain fatty acid transport; very long-chain fatty acid metabolic process; fatty acid metabolic process
Cellular component: endoplasmic reticulum membrane; plasma membrane; sarcolemma
Genetic constraint (gnomAD): Loss-of-function variants: 47 observed, 43.14 expected, observed/expected ratio (o/e) 1.09, 90% interval 0.86 to 1.39. The upper end of that interval is the gene's LOEUF score, 1.39, which puts it in group 5 of 6, group 1 being the genes least tolerant of losing a copy. Missense variants: 628 observed, 591.68 expected, observed/expected ratio (o/e) 1.06, 90% interval 0.99 to 1.13. Synonymous variants: 235 observed, 216.6 expected, observed/expected ratio (o/e) 1.09, 90% interval 0.98 to 1.21.
Homologues: Orthologues: chimpanzee SLC27A6 (99% identical), macaque SLC27A6 (95% identical), dog SLC27A6 (83% identical), rabbit SLC27A6 (82% identical), pig SLC27A6 (79% identical), guinea pig SLC27A6 (79% identical), mouse Slc27a6 (78% identical), rat Slc27a6 (78% identical), tropical clawed frog slc27a6 (65% identical), zebrafish slc27a6 (56% identical), Drosophila melanogaster Fatp1 (36% identical), Drosophila melanogaster Fatp2 (36% identical), and 22 more. Paralogues in human: SLC27A2 (51% identical), SLC27A3 (45% identical), SLC27A5 (43% identical), SLC27A4 (39% identical), SLC27A1 (37% identical), ACSL6 (21% identical), ACSL5 (20% identical), ACSL1 (20% identical), ACSL3 (18% identical), ACSBG1 (17% identical), ACSL4 (17% identical), ACSBG2 (16% identical).
Diseases named in the same sentence as SLC27A6 in open-access papers:
SLC27A6 is named in the same sentence as 20 diseases in open-access papers, as found by Europe PMC text mining. Sharing a sentence is not in itself a finding about the gene and the disease. The quoted sentences say what the papers report.
breast carcinoma (4 papers, 2020 to 2023). "It has been reported that Slc27a6 expression is downregulated in breast cancers, but this is the first finding in intestinal tumors." (PMID 37824459, 2023). "ARFGEF2:SULF2 fusion was also called for MCF-7 cell line and SLC27A6:ADAMTS19 was previously identified in breast cancer with short reads." (PMID 35164688, 2022). "On the other hand, SLC27A6 was decreased in esophageal squamous cell carcinoma and breast cancer cells." (PMID 35047398, 2021). "Previously, SLC27A6 was only reported to be downregulated in breast cancer, suggesting that the role of this protein may change in different tumor environments." (PMID 32922552, 2020). "Downregulated SLC27A6 inhibited cell proliferation and FA uptake in non-cancerous breast cells but did not affect tumor growth and lipid metabolism in breast cancer." (PMID 35047398, 2021).
prostate carcinoma (4 papers, 2021 to 2023). A carcinoma that arises from epithelial cells of the prostate gland. "SLC27A6 is used as a predictor in the genetic analysis of colorectal cancer, prostate cancer, pancreatic cancer, and other tumors." (PMID 36105089, 2022). "SLC27A6 expression was highly increased in enzalutamide-resistant prostate cancer." (PMID 35047398, 2021). "A current study in prostate cancer proposed that the abnormal expression of SLC12A5, SLC25A17, and SLC27A6 were strong to metabolic reprogramming and the development of resistance against chemotherapeutic drugs." (PMID 38136890, 2023).
colorectal cancer (2 papers, 2021 to 2022). A primary or metastatic malignant neoplasm that affects the colon or rectum. "SLC27A6 promoter hypermethylation was firstly reported in colorectal cancer." (PMID 35047398, 2021).
nasopharyngeal carcinoma (2 papers, 2021 to 2023). A carcinoma arising from the nasopharyngeal epithelium. "For example, solute carrier family 27 member 6 (SLC27A6) increased the levels of triglyceride (TG) and total cholesterol (T-CHO) in nasopharyngeal carcinoma (NPC) cells by promoting lipid biosynthesis." (PMID 37394582, 2023).
atrial fibrillation (1 paper, 2021). A disorder characterized by an electrocardiographic finding of a supraventricular arrhythmia characterized by the replacement of consistent P waves by rapid oscillations or fibrillatory waves that vary in size, shape and timing and are accompanied by an irregular ventricular response. "Trait associations were found for five loci: the SNV at TMEM44 was associated with diastolic blood pressure, SLC27A6 with red cell distribution, NKX2–5 with heart rate and atrial fibrillation, and finally NUFIP2 with mean platelet volume." (PMID 34274964, 2021).
cardiac hypertrophy (1 paper, 2021). "Differential expression of SLC27A6 knockdowns predicted significant upregulation of the “Cardiac hypertrophy signaling” and “Role of NFAT in cardiac hypertrophy” pathways (z-scores +1.9 and +1.7, respectively)." (PMID 33679876, 2021).
diabetes (1 paper, 2019). "At E10.5, effects of diabetes were significant for Slc27a6/Fatp6, Slc27a4/Fatp4, and Cpt2 (27.8%, 19.4%, and 19.7%, respectively), and for Cpt1a, Slc2a13/Glut13, and Cpt1b, diet was a significant contributor (42.9%, 38.7%, and 31%, respectively)." (PMID 31774824, 2019). "Except for the influence of diabetes on Cd36, Scl27a5/Fatp5 and Slc27a6/Fatp6 at E18.5, the effects of diet on fatty acid transporter expression levels were normalized towards the end of pregnancy." (PMID 31774824, 2019).
endometritis (1 paper, 2021). An acute or chronic, usually bacterial infectious process affecting the endometrium. "Similarly, expressions of IFNT, ISG15, CXCL10, PPARG, RXRG, SLC2A1, and SLC27A6 proteins were greater and MUC1 was lower in the endometrium of cows without endometritis compared with cows with endometritis (p < 0.05)." (PMID 33920430, 2021).
glioblastoma (1 paper, 2023). The most malignant astrocytic tumor (WHO grade IV). "The expression of SLC27A4 and SLC27A6 was lower in glioblastoma tumors compared to the peritumoral area." (PMID 37239243, 2023). "We also found lower expression of SLC27A6 in the glioblastoma compared to the peritumoral area." (PMID 37239243, 2023). "In female patients with glioblastoma, a positive correlation was found between the expression of SLC27A4, SLC27A5, and SLC27A6 and the number of cigarette packs smoked in their lifetime." (PMID 37239243, 2023). "In women, there was a positive correlation between the expression of SLC27A4, SLC27A5, and SLC27A6 with cigarette smoking in all investigated regions of the glioblastoma tumor and in the peritumoral area, whereas no such relationship was observed in men." (PMID 37239243, 2023). "Similarly to the analysis of all patients, male samples showed a positive correlation of SLC27A1 expression with SLC27A3, SLC27A4 with SLC27A5, SLC27A4 with SLC27A6, and SLC27A5 with SLC27A6 in the studied regions of the glioblastoma tumor." (PMID 37239243, 2023).
leukodystrophy (1 paper, 2016). Leukodystrophies are a group of rare, progressive, metabolic, genetic diseases that affect the brain, spinal cord and often the peripheral nerves. "The scarcity of mutant alleles in the human population, coupled with a paucity of diagnostic sequence data in affected individuals and an incompletely penetrant phenotype, provides an explanation for the failure (until now) to associate SLC27a6 with leukodystrophy." (PMID 26893370, 2016). "Finally, in an extension of our model system to the study of human disease, we describe our identification of an individual with leukodystrophy who harbors a rare mutation in SLC27a6 (encoding a very-long-chain ACS), a human homolog of bgm and dbb." (PMID 26893370, 2016). "Finally, in light of the specific bgm, dbb and fatp shared loss-of-function phenotypes in flies, it is noteworthy that our patient study reveals a correlation of SLC27a6, the human fatp ortholog, with leukodystrophy in humans." (PMID 26893370, 2016).
mycobacterial infection (1 paper, 2025). "Additionally, the genes Mgll, Dgat2, Slc27a6, and Stard10 have been implicated in lipid metabolism, indicating that lipid metabolism may be disrupted in Gpr84−/− BMDMs during mycobacterial infection." (PMID 39858878, 2025).
thyroid cancer (1 paper, 2020). "We first analyzed the only upregulated SLC27A6, and revealed 703 and 2605 negatively and positively correlated genes in thyroid cancers (Pearson CC greater than 0.3), respectively." (PMID 32922552, 2020).
tumor (6 papers, 2020 to 2023). "In male patients, the expression of SLC27A6 in the tumor core was lower than in the peritumoral area (p = 0.0009)." (PMID 37239243, 2023). "Women also showed a negative correlation in the expression of SLC27A3 in the peritumoral area with the expression of SLC27A4, SLC27A5, and SLC27A6 in the enhancing tumor region." (PMID 37239243, 2023). "In women, there was a positive correlation between ELOVL1 expression and SLC27A, SLC27A5, and SLC27A6 expression in the tumor core." (PMID 37239243, 2023). "In female patients, the expression of SLC27A6 in the enhancing tumor region was lower than in the peritumoral area (p = 0.04)." (PMID 37239243, 2023). "In women, a positive correlation was observed between the expression of ELOVL1 and SLC27A4, SLC27A5, and SLC27A6 in the tumor core." (PMID 37239243, 2023). "Although the calculated p-value of SLC27A6 was less than 0.05, it expressed lower in tumor tissues, and the lower expression of SLC27A6 suggested better survival performance." (PMID 35927229, 2022). "SLC27A6 overexpression repressed cell proliferation and colony formation in vitro and inhibited tumor growth in vivo." (PMID 35047398, 2021). "We further confirmed that SLC27A6 overexpression was significantly suppressed the xenograft tumor growth and tumor size in vivo." (PMID 35047398, 2021). "Re-expression of SLC27A6 significantly inhibited cell proliferation and clonogenicity but promoted tumor migration and invasion both in vitro and in vivo." (PMID 35047398, 2021). "Additionally, in the enhancing tumor region, there was a positive correlation between the expression of SLC27A6 and age." (PMID 37239243, 2023). "Similarly, the expression of SLC27A6 was also significantly lower in the enhancing tumor region and the tumor core compared to the peritumoral area (p = 0.014 and p = 0.0019, respectively)." (PMID 37239243, 2023). "Additionally, the expression of SLC27A6 in the tumor core was lower than in the enhancing tumor region (p = 0.006)." (PMID 37239243, 2023). "As SLC27A6 overexpression displayed inhibition ability of tumor growth in vitro, we investigated whether SLC27A6 had similar effects in vivo." (PMID 35047398, 2021). "Thus, it was reasonable to suppose that SLC27A6 enhanced lipid storage and provided insufficient FAs for tumor growth, and negatively regulated the ROS pathway." (PMID 35047398, 2021). "However, SLC27A6 overexpression exhibited pro-metastatic functions by promoting tumor migration and invasion in vitro and facilitating EMT of metastatic lesions in vivo." (PMID 35047398, 2021). "Additionally, there was a correlation of SLC27A6 between the peritumoral area and the tumor core." (PMID 37239243, 2023). "Notably, SLC27A6 expressed lower in TCGA tumor samples than in GSE40435 tumor tissues." (PMID 35927229, 2022). "Positive correlations were observed between SLC27A4 and SLC27A5, SLC27A4 and SLC27A6, and SLC27A5 and SLC27A6 in all three tumor regions." (PMID 37239243, 2023). "For example, a positive correlation was found between SLC27A3 in the enhancing tumor region and SLC27A1 in the tumor core, and between SLC27A4 in the peritumoral area and SLC27A6 in the tumor core." (PMID 37239243, 2023). "Of the Unidentified tumors from the non-irradiated group, region 18qB1 was deleted in Tumor IDs 0-1-3, 0-1-11, and 0-1-12 (mean deletion size; 47 ± 0.87 kbp); this region contains part of the gene Slc27a6." (PMID 37824459, 2023). "A negative correlation was found between SLC27A1 in the peritumoral area and SLC27A6 in the tumor core, between SLC27A3 in the enhancing tumor region and SLC27A5 and SLC27A6 in the tumor core, and between SLC27A3 in the tumor core and SLC27A5 in the peritumoral area." (PMID 37239243, 2023).
tumor (continued). "Additionally, there was a positive correlation between SLC27A5 expression in the tumor core and SLC27A6 expression in the peritumoral area and between SLC27A5 expression in the peritumoral area and SLC27A6 expression in the tumor core." (PMID 37239243, 2023). "In addition, re-expression of SLC27A6 had an anti-tumorigenic role in repressing proliferation in NPC cells and inhibited tumor growth in xenografts." (PMID 35047398, 2021). "To some extent, we speculated SLC27A6 promoted NPC metastasis via increasing CD24 and CD44 positive tumor stem cells." (PMID 35047398, 2021). "In particular, ectopic expression of SLC27A6 markedly suppressed expression of epithelial marker (E-cadherin), but increased expression of EMT transcription factors (Snail) and enhanced expression of β-catenin signaling in xenograft tumor." (PMID 35047398, 2021). "Here, we showed that overexpression of SLC27A6 induced EMT in NPC cells by interfering with E-cadherin expression, upregulating with EMT transcription factors (Snail), and activating β-catenin signaling, could result in tumor metastasis in vivo." (PMID 35047398, 2021). "A positive correlation was observed between the expression of SLC27A1 and SLC27A3 in the enhancing tumor region, while a negative correlation was found with the expression of SLC27A4, SLC27A5, and SLC27A6." (PMID 37239243, 2023).
cancer (3 papers, 2020 to 2022). A tumor composed of atypical neoplastic, often pleomorphic cells that invade other tissues. "The direct link between SLC27A6 expression and CSC markers indicated that SLC27A6 was associated with cancer metastasis ability." (PMID 35047398, 2021). "Among these genes, 18 cancer driver genes showed a dual role associated with epigenetic changes, five of which were considered to be critical: SLC27A6, PDGFRA, GAS7, PLXNC1, and NRP2." (PMID 31900418, 2020). "Overexpression of SLC27A6 also increased FA uptake, negatively regulated ROS level and positively correlated with cancer stem cell (CSC) markers in NPC cells." (PMID 35047398, 2021). "Notably, the mRNA level of SLC27A6 was positively correlated with cancer stem cell (CSC) markers, CD24 and CD44." (PMID 35047398, 2021). "The excessive LDs could upregulate CD24, CD44 expression and promote maintaining NPC CSC stemness, which could be a possible mechanism explaining why SLC27A6 overexpression promoted cancer metastasis." (PMID 35047398, 2021). "The new findings provided a complex insight into SLC27A6 regulating NPC development and progression, which involved lipid metabolism in clinical cancer therapy." (PMID 35047398, 2021). "On the other hand, oleic acid (C18:1), which has antitumor effects in several types of cancers, is a preferred substrate of SLC27A1 and SLC27A6, but not SLC27A4." (PMID 36005596, 2022).
infection (1 paper, 2013). The state of being infected such as from the introduction of a foreign agent such as serum, vaccine, antigenic substance or organism. "The siRNA screen and RNA expression analysis revealed roles for a subset of long chain acyl-CoA synthetases following infection: SLC27A6 and ACSL1 were both siRNA hits and increased at the mRNA level, and SLC27A3 was an siRNA hit but not increased in mRNA abundance." (PMID 23696731, 2013).
SLC27A6 also shares sentences with these, for which no sentence is quoted: heart failure (1 paper); intestinal tumors (1); left ventricular hypertrophy (1); Obesity (1); pancreatic cancer (1).